ISM1 (isthmin 1)
Diseases named in the same sentence as ISM1 in open-access papers (continued):
Sharing a sentence is not in itself a finding about the gene and the disease.
chronic hepatitis B (1 paper, 2025). "In conclusion, in our study, we observed that the immunoreactivities of PODXL, PTX3, and ISM1 in liver tissue were increased in fibrotic livers associated with chronic hepatitis B, compared to liver tissues with normal or low-grade fibrosis." (PMID 41462970, 2025). "In our study, we observed increased ISM1 immunoreactivity in liver tissues with moderate to advanced fibrosis induced by chronic hepatitis B (CHB)." (PMID 41462970, 2025). "In our study, the immunoreactivities of Podocalyxin, Isthmin-1, and Pentraxin-3 in the liver tissues of patients with chronic hepatitis B and high-grade fibrosis were found to be increased compared to those with low-grade fibrosis and the control group." (PMID 41462970, 2025). "We aimed to evaluate the immunoreactivities of podocalyxin, Isthmin-1, and pentraxin-3 in the liver tissue of patients with chronic hepatitis B. Materials and Methods: Power analysis was performed (effect size (f = 0.5), (α) = 0.05 and statistical power of 0.80)." (PMID 41462970, 2025).
Crohn disease (1 paper, 2025). A gastrointestinal disorder characterized by chronic inflammation involving all layers of the intestinal wall, noncaseating granulomas affecting the intestinal wall and regional lymph nodes, and transmural fibrosis. "Therefore, the proper study of Isthmin-1 in intestinal diseases, such as inflammatory bowel disease, Crohn’s disease, and various types of intestinal cancer, could open the possibility of using this molecule as both a diagnostic biomarker and a potential therapeutic tool." (PMID 40572169, 2025).
glioma (1 paper, 2023). A benign or malignant brain and spinal cord tumor that arises from glial cells (astrocytes, oligodendrocytes, ependymal cells). "Moreover, administration of recombinant ISM1 could inhibit glioma growth by anti-angiogenesis with no significant side effects, which further proved the anti-angiogenic ability of ISM1." (PMID 36995541, 2023).
Hypertension (1 paper, 2024). The presence of chronic increased pressure in the systemic arterial system. "After adjustment for age, history of hypertension, waist circumference, TG, HDL-c, eGFR, and HOMA-IR, decreased ISM1 remained an independent risk factor for IPH in men." (PMID 39119006, 2024). "The higher level of ISM1 in men remained significant even after adjustment for age, history of hypertension, TG, HDL-c, eGFR, BMI, waist circumference and HOMA-IR (P <0.05)." (PMID 39119006, 2024). "However, in men, an increasing level of ISM1 was found to be significantly associated with a reduced risk of IPH (P=0.006) after correcting for age, history of hypertension, waist circumference, TG, HDL-c, eGFR and HOMA-IR." (PMID 39119006, 2024).
liver fibrosis (1 paper, 2025). "Emerging evidence points to a potential role for ISM1 in liver fibrosis, particularly through its involvement in the activation of hepatic stellate cells (HSCs), which are central mediators of fibrogenesis." (PMID 41462970, 2025).
lung diseases (1 paper, 2022). "The elevated ISM1 level in AECII was accountable for hypoxia triggered PMVEC monolayer hyperpermeability in an AECII/PMVEC co-culture system that indicated substantial function of alveolar epithelial cells and a modulatory role of ISM1 in hyperpermeability featured lung diseases." (PMID 36611811, 2022).
lung fibrosis (1 paper, 2022). "ISM1 deficiency also lead to intensified post-ALI pulmonary fibrosis in mice." (PMID 35752760, 2022). "In addition, in both single-dose and repeated-dose intratracheal LPS challenge experiments, we observed a heightened lung fibrosis at 28 days post first LPS-challenge in Ism1−/− lung, which are represented by higher collagen deposition and obvious scar structure formation." (PMID 35752760, 2022). "However, Ism1−/− lungs exhibited prolonged and heightened lung fibrosis and scar formation." (PMID 35752760, 2022). "Nevertheless, this work revealed ISM1 as a novel lung endogenous protein that plays a role in restraining LPS-triggered acute lung inflammation, ALI and post-ALI pulmonary fibrosis." (PMID 35752760, 2022). "This work demonstrated that ISM1 is a protective factor in mouse lung, restraining the level of inflammatory response in LPS-induced ALI and limiting post-injury pulmonary fibrosis by suppressing LPS-triggered production of pro-inflammatory cytokines and NF-κB activation." (PMID 35752760, 2022). "However, what role ISM1 plays in ALI/ARDS and lung fibrosis remain unclear." (PMID 35752760, 2022).
periodontitis (1 paper, 2025). An acute or chronic inflammatory process that affects the tissues that surround and support the teeth. "Importantly, our study demonstrates that ISM1 and MMP-8 levels in GCF reflect the severity of periodontitis, as evidenced by their strong positive association with clinical parameters such as PD and CAL." (PMID 41063065, 2025).
renal agenesis (1 paper, 2023). Renal agenesis (RA) is a form of renal tract malformation characterized by the complete absence of development of one or both kidneys (unilateral RA or bilateral RA respectively), accompanied by absent ureter(s). "Mice deficient for Ism1 exhibit defective ureteric bud bifurcation and impaired metanephric mesenchyme condensation in E11.5 embryos, attributable to the compromised Gdnf/Ret signaling, ultimately leading to renal agenesis and hypoplasia/dysplasia." (PMID 37185772, 2023). "Gross morphological examination of Ism1−/− mice showed significant kidney defects ranging from renal hypoplasia, dysplasia, unilateral renal agenesis (URA) to bilateral renal agenesis (BRA)." (PMID 37185772, 2023). "In addition, though renal agenesis was observed in neither Integrin α3 nor α6 deficiency mutant mice, loss of Integrin α8 or its ligand Npnt both give rise to kidney agenesis with a penetrance similar to that in Ism1 deficient mice." (PMID 37185772, 2023).
Sepsis (1 paper, 2022). Sepsis is defined as life-threatening organ dysfunction caused by a dysregulated host response to infection. "ISM1+ cells are involved in the response to a bacterial challenge, suggesting an association between ISM1-producing cells and dangerous inflammatory responses like sepsis." (PMID 35402623, 2022). "We also observed that ISM1+ cells express TLR4, TLR5, and TLR9, and, in a mouse model of sepsis induced by P. aeruginosa, we observed that all the LSK and ISM1+LSK cells were affected." (PMID 35402623, 2022).
tumor (16 papers, 2017 to 2026). "ism1 is also implicated in angiogenesis; addition of ISM1 protein into matrigel plugs with murine tumors resulted in decreased endothelial capillary networks and decreased overall tumor growth." (PMID 29758043, 2018). "Isthmin-1 (ISM1) has been associated with a range of biological and pathological processes, including metabolic regulation, immune response modulation, tumor development, cellular proliferation, and the control of endothelial barrier permeability." (PMID 41462970, 2025). "What's important, both of the receptors can mediate ISM1 internalization and accelerate apoptosis of activated EC cells and tumor cells." (PMID 35958402, 2022). "Hsa_circ_0091570 can also act as a ceRNA to bind miR-1307 and upregulate the expression of isthmin 1 (ISM1) to inhibit tumor progression." (PMID 34540684, 2021). "Multivariate analysis showed that ISM1, tumor size and lymph node involvement were all independent prognostic factors." (PMID 34350177, 2021). "Another difference across species is the description of ism1 as an angiogenesis inhibitor; in mice exogenous ISM1 suppressed tumor angiogenesis, but in zebrafish the knockdown of ism1 reduced the growth of intersegmental vessels." (PMID 29758043, 2018). "ISM1 not only influences energy metabolism, regulating glucose, lipid, and protein synthesis, but also modulates cellular processes and fundamental functions, such as apoptosis and angiogenesis, making it a key player in tumor progression." (PMID 40572169, 2025). "This suggests that ISM1 may be an endogenous inhibitor of angiogenesis, which could provide a direction for future tumor therapy, but the anti-angiogenic effect of ISM1 in other types of tumors remains to be explored." (PMID 36995541, 2023). "Additionally, rISM1 is reported to inhibit vascular endothelial growth factor (VEGF)-mediated angiogenesis, while overexpression of ISM1 suppressed tumour angiogenesis in B16 melanoma cells and tumour growth in mice." (PMID 36611811, 2022). "In addition, hsa_circ_0091570 modulate the expression of ISM1 by sponging miR-1307 to exert tumor-suppressing capacity in the mouse xenograft model of HCC." (PMID 34133325, 2021). "In TCGA cohort, after comparing the expression of ISM1 among cases with different clinicopathological characteristics, we found that expression was higher in patients with age < 60 (P < 0.05), a larger tumor size (P < 0.05), lymph node involvement (P < 0.001), and advanced stages (P < 0.01)." (PMID 34350177, 2021). "Several of the genes upregulated in CTNNB1-mutated tumours have previously been described as overexpressed in CTNNB1-mutated adrenal lesions, regardless of type of hormone production or differentiation level: AFF3, ISM1, NKD1, ENC1 and RALBP131,32." (PMID 31000732, 2019). "Although detailed biological function of the association between H19 and ISM1 has not been illustrated, it has been proposed that this association regulates GC cell growth and mobility because ISM1 regulates surviving and apoptosis in many tumor cells." (PMID 28230721, 2017). "A relationship between the upregulation of Isthmin 1 (ISM1) in CRC and tumor angiogenesis was also described." (PMID 36286020, 2022). "ISM1 was selected as a negative prognosis factor in a previously published 21-gene signature related to the UM tumor microenvironment, while MTUS1 and IL12RB2 were considered as indicators of favorable prognosis." (PMID 38339073, 2024). "Furthermore, it was also demonstrated that ISM1 activated the HUVEC apoptosis through the caspase-3 pathway, and thus, inhibits tumour angiogenesis in vivo." (PMID 36611811, 2022). "AMOP-containing proteins have conserved cysteine (C) residues, while AMOP in both ISM1 and ISM2 also possesses a KGD motif that binds to the integrin αIIbβ3 present in the multiple antagonists of platelet aggregation and is engaged in the integrin-mediated cellular adhesion and tumour metastasis." (PMID 36611811, 2022).
tumor (continued). "Furthermore, ISM1 induced EC apoptosis mediated by αvβ5 integrin in the presence of VEGF, βFGF or serum and marginally induced fibroblast apoptosis in the presence of serum, but did not induce apoptosis of tumor cells." (PMID 35958402, 2022).
cancer (9 papers, 2017 to 2025). A tumor composed of atypical neoplastic, often pleomorphic cells that invade other tissues. "Enrichment analysis showed that multiple cancer-related pathways and immune-related pathways were closely associated with ISM1." (PMID 34350177, 2021). "The GSEA results showed that multiple cancer-related pathways were significantly associated with ISM1, including EMT, hypoxia, the KRAS signaling pathway, angiogenesis, the Notch signaling pathway, and the Hedgehog signaling pathway." (PMID 34350177, 2021). "In addition, 71% of the genes in the cancer-related signaling pathway epithelial-mesenchymal transition (EMT) is associated with ISM1, while EMT also induces Treg cells and dendritic cells and regulates immune responses." (PMID 36995541, 2023). "In the GSEA results, enriched pathways, such as the EMT, hypoxia, KRAS signaling, angiogenesis, Notch and Hedgehog signaling pathways, were significantly positively associated with ISM1, and most of these pathways are vital to cell proliferation, migration and resistance in cancer, including CRC." (PMID 34350177, 2021). "This is the first study to find that ISM1 is associated with multiple important cancer-related pathways, especially EMT, and multiple important immunosuppressive signaling pathways, which provides us with evidence supporting application of ISM1 inhibitors in CRC immunotherapy." (PMID 34350177, 2021). "Current research on the biological functions of ISM-1 primarily focuses on its roles in growth and development, metabolism, and cancer treatment." (PMID 41462970, 2025). "ISM-1 affects cellular processes such as autophagy, angiogenesis, and the immune microenvironment, particularly in cancer progression." (PMID 41462970, 2025). "ISM1 affects cancer development by regulating cellular autophagy, angiogenesis, and the immune microenvironment." (PMID 36995541, 2023). "Over the past few years, multiple studies have focused on the functional analysis of ISM1 in several events, including angiogenesis, metabolism, organ homeostasis, immunity, craniofacial development, and cancer." (PMID 36611811, 2022). "Enrichment analysis showed that ISM1 upregulation was positively correlated with cancer-related pathways, such as EMT, hypoxia, and the Notch and KRAS signaling pathways." (PMID 34350177, 2021). "In recent years, growing evidence has shown that aberrant expression of ISM1 can affect the biological behavior of cancer." (PMID 34350177, 2021). "Subsequently, csGRP78 was identified as a high-affinity receptor for ISM1, and ISM1/csGRP78 interaction triggers apoptosis in both activated endothelial cells and cancer cells that harbor high levels of csGRP78." (PMID 31766302, 2019). "In recent years, ISM1 has been found to play an important role in anti-angiogenesis, regulation of immune response, and promotion of apoptosis; thus, it has been found to have great anti-cancer potential." (PMID 36995541, 2023). "In this article, we searched the relevant literature of ISM1 in growth and development, glycolipid metabolism, anti-cancer and other functions from 2002 to 2022 through PubMed, China Knowledge Network, Web of Science, Google Scholar and Baidu Academic databases and sorted them out." (PMID 36995541, 2023). "In addition, ISM1 plays an important role in cancer development by promoting apoptosis and anti-angiogenesis, and by regulating multiple inflammatory pathways to influence the body's immune response." (PMID 36995541, 2023). "In addition, it is unclear whether the dual role of ISM1 is due to the difference in disease classes or cancer cell types, or due to downstream levels of targeting in the pathways, and further studies are needed in the future to elucidate this." (PMID 36995541, 2023).
cancer (continued). "Finally, the early VEGF up-regulation and the late VEGF down-regulation mediated by sAPPα suggest a physiologic fine-tuning of its production in which isthmins may play a possible important role (although available data are limited to ISM1 and cancer context)." (PMID 37047617, 2023). "Briefly, ISM1 could be a potential therapeutic target for cancer." (PMID 35958402, 2022). "Furthermore, another study has also reported the elevated expression of ISM1 in the CRC tissue of patients, and on the top of that, the positive correlation of ISM1 with cancer-associated signalling pathways including EMT, hypoxia, KRAS, Notch, and Hedgehog was observed." (PMID 36611811, 2022). "However, over the past few years, increasing evidence has revealed that the atypical expression of ISM1 may affect cancer." (PMID 36611811, 2022). "Furthermore, a recent study has also reported the elevated expression of ISM1 in the CRC tissue of patients, and on top of that, a positive correlation of ISM1 with cancer-associated signalling pathways including EMT, hypoxia, KRAS, Notch, and Hedgehog were observed." (PMID 36611811, 2022). "In addition, a previous study reported that ISM1 activates the Src pathway through the novel ISM-GRP78 apoptosis pathway, triggering apoptosis not only in endothelial cells but also in in cancer cells with an elevated expression of cell-surface GRP78." (PMID 36611811, 2022). "Finally, despite the negative correlation between ISM1/Isthmin 1 and VEGF in cancer context, literature data correlating ISM2/Isthmin 2 with VEGF are still lacking, although a possible interaction could be hypothesised based on its pro- or anti-angiogenic properties." (PMID 37047617, 2023).
infection (4 papers, 2022 to 2025). The state of being infected such as from the introduction of a foreign agent such as serum, vaccine, antigenic substance or organism. "Since ISM1 expression changed during inflammatory processes involving chronic diseases but also during pathogenic challenges, we decided to investigate whether ISM1 expression in the small intestine is perturbed during infection." (PMID 40572169, 2025). "We also examined the impact of infection on subpopulations of cells with a hematopoietic stem-like phenotype that expressed ISM1 by analyzing different progenitor cell markers." (PMID 40572169, 2025). "We found a variety of ISM1+-expressing cells, including CD45+ cells, EpCAM+ cells, and, importantly, we also found different subsets of cells carrying hematopoietic stem cell markers (LSKs) expressing ISM1, and their frequency was perturbed during infection." (PMID 40572169, 2025). "Importantly, the infected mice presented a significant increase in the levels of ISM1, suggesting a possible role for ISM1 in the response to infection." (PMID 40572169, 2025). "Our data showed an increase in the LSK ISM1+ and CD45+Lin-150+ISM1+ cell populations, indicating that the infection may also affect the homeostasis of intestinal ISM1+ HSCs." (PMID 40572169, 2025). "We found that the fraction of CD45+ISM1+ cells increased significantly during infection and, importantly, ISM1+LSK cells were also significantly increased, suggesting that the fraction of hematopoietic stem-like cells expressing ISM1 was perturbed during infection." (PMID 40572169, 2025). "We have observed that ISM1 levels decrease during infections and that these cells express pattern recognition receptors (PRRs), suggesting that they may play a role in modulating the immune response." (PMID 40572169, 2025). "Consequently, a detailed exploration of the function of ISM1 in lung extramedullary hematopoiesis during both homeostasis and infection/inflammation will help to define the function(s) of ISM1 in this emerging area." (PMID 35402623, 2022). "The results showed that the CD45+Lin-CD34+ISM1+ population tended to decrease during infection, while the CD45+Lin-CD150+ISM1+ populations significantly increased during infection." (PMID 40572169, 2025). "Furthermore, under bacterial infection, populations with a hematopoietic stem phenotype are disrupted, such as ISM1+ LSK and CD45+ Lin-150+ ISM1+ cells, which were increased during infection." (PMID 40572169, 2025). "S. maltophilia strains from the Sm2 cluster (ism1 and msm2) bound poorly to polarized epithelium, which did not change following infection with P. aeruginosa." (PMID 37942787, 2023).
metabolic disease (4 papers, 2023 to 2025). A congenital disorder (due to inherited enzyme abnormality) or acquired (due to failure of a metabolically important organ) disorder resulting from an abnormal metabolic process. "Studies have demonstrated reduced ISM1 in inflammatory conditions and its protective effects in lung homeostasis and metabolic disorders." (PMID 41277950, 2025). "Multiple forms of exercise play a role in metabolic diseases, and it is unknown whether exercise has an effect on ISM1, thus improving metabolic diseases." (PMID 36995541, 2023).